KCNMA1 (potassium calcium-activated channel subfamily M alpha 1)
Description:
Potassium channel activated by both membrane depolarization or increase in cytosolic Ca(2+) that mediates export of K(+). It is also activated by the concentration of cytosolic Mg(2+). Its activation dampens the excitatory events that elevate the cytosolic Ca(2+) concentration and/or depolarize the cell membrane. It therefore contributes to repolarization of the membrane potential. Plays a key role in controlling excitability in a number of systems, such as regulation of the contraction of smooth muscle, the tuning of hair cells in the cochlea, regulation of transmitter release, and innate immunity. In smooth muscles, its activation by high level of Ca(2+), caused by ryanodine receptors in the sarcoplasmic reticulum, regulates the membrane potential. In cochlea cells, its number and kinetic properties partly determine the characteristic frequency of each hair cell and thereby helps to establish a tonotopic map. Kinetics of KCNMA1 channels are determined by alternative splicing, phosphorylation status and its combination with modulating beta subunits. Highly sensitive to both iberiotoxin (IbTx) and charybdotoxin (CTX). Possibly induces sleep when activated by melatonin and through melatonin receptor MTNR1A-dependent dissociation of G-beta and G-gamma subunits, leading to increased sensitivity to Ca(2+) and reduced synaptic transmission. [Isoform 5]: Potassium channel activated by both membrane depolarization or increase in cytosolic Ca(2+) that mediates export of K(+).
Synonyms: MaxiK; hSlo; SLO; KCa1.1; mSLO1; BKTM; CADEDS; IEG16; LIWAS; PNKD3; SAKCA; SLO-ALPHA; SLO1; bA205K10.1
Tractability: Small molecule: a drug acting on it is in phase 2 or 3 trials; a structure with a bound ligand is known; a high-quality ligand is known; it has a binding pocket of medium quality; it belongs to a druggable protein family. Antibody: UniProt places it where antibodies can reach, with high confidence; its Gene Ontology location is reachable by antibodies, with high confidence; UniProt predicts a signal peptide or a membrane-spanning region. PROTAC: its protein half-life has been measured; a small molecule that binds it is known.
Target class: Voltage-gated ion channel; Ion channel; Calcium-activated potassium channel; Potassium channels
Safety:
Unwanted effects reported when the protein is acted on. In parentheses: how it was acted on, where the effect was seen, and who reports it.
angioedema (source: ClinPGx)
Gene: Protein-coding gene on chromosome 10 (76,869,601 to 77,638,369, reverse strand). Ensembl gene ENSG00000156113.
Subcellular location: Cell membrane
Pathways (Reactome):
Sensory Perception: Acetylcholine inhibits contraction of outer hair cells; Sensory processing of sound by inner hair cells of the cochlea
Hemostasis: cGMP effects
Neuronal System: Ca2+ activated K+ channels
Gene Ontology:
Molecular function: actin binding; calcium-activated potassium channel activity; large conductance calcium-activated potassium channel activity; protein binding; voltage-gated potassium channel activity; monoatomic ion channel activity
Biological process: intracellular potassium ion homeostasis; micturition; negative regulation of cell volume; positive regulation of apoptotic process; potassium ion transport; regulation of membrane potential; response to calcium ion; response to carbon monoxide; response to hypoxia; response to osmotic stress; smooth muscle contraction involved in micturition; potassium ion transmembrane transport; vasodilation; monoatomic ion transport; transmembrane transport
Cellular component: apical plasma membrane; caveola; membrane; voltage-gated potassium channel complex; plasma membrane; postsynaptic membrane
Genetic constraint (gnomAD): Loss-of-function variants: 26 observed, 109.08 expected, observed/expected ratio (o/e) 0.24, 90% interval 0.17 to 0.33. The upper end of that interval is the gene's LOEUF score, 0.33, which puts it in group 1 of 6, group 1 being the genes least tolerant of losing a copy. Missense variants: 760 observed, 1,437.9 expected, observed/expected ratio (o/e) 0.53, 90% interval 0.5 to 0.56. Synonymous variants: 539 observed, 561.37 expected, observed/expected ratio (o/e) 0.96, 90% interval 0.89 to 1.03.
Gene-disease validity (ClinGen):
ClinGen rates the evidence that KCNMA1 causes each of these diseases.
generalized epilepsy-paroxysmal dyskinesia syndrome (autosomal dominant): Definitive. Generalized epilepsy-paroxysmal dyskinesia syndrome is characterized by the association of paroxysmal dyskinesia and generalized epilepsy (usually absence or generalized tonic-clonic seizures) in the same individual or family.
generalized epilepsy-paroxysmal dyskinesia syndrome (autosomal recessive): Moderate.
Homologues: Orthologues: macaque KCNMA1 (99% identical), chimpanzee KCNMA1 (99% identical), dog KCNMA1 (99% identical), pig KCNMA1 (99% identical), rat Kcnma1 (94% identical), rabbit KCNMA1 (89% identical), tropical clawed frog kcnma1 (86% identical), guinea pig KCNMA1 (86% identical), mouse Kcnma1 (84% identical), zebrafish kcnma1a (84% identical), zebrafish kcnma1b (36% identical), Drosophila melanogaster SLO2 (19% identical), and 1 more. Paralogues in human: KCNU1 (39% identical), KCNT1 (20% identical), KCNT2 (20% identical).
Diseases named in the same sentence as KCNMA1 in open-access papers:
KCNMA1 is named in the same sentence as 223 diseases in open-access papers, as found by Europe PMC text mining. Sharing a sentence is not in itself a finding about the gene and the disease. The quoted sentences say what the papers report.
epilepsy (49 papers, 2008 to 2025). A brain disorder characterized by episodes of abnormally increased neuronal discharge resulting in transient episodes of sensory or motor neurological dysfunction, or psychic dysfunction. "KCNMA1-N999S (also called N995S and N1053S in alternate reference transcripts) causes epilepsy and paroxysmal dyskinesia and is the most commonly identified pathogenic de novo variant in the KCNMA1 gene." (PMID 40785052, 2025). "In contrast, gain-of-function mutations of KCNMA1 are associated with paroxysmal dyskinesia, epilepsy, and dystonia." (PMID 37374132, 2023). "Changes in BK channel function and/or KCNMA1 expression are associated with a growing number of neurodevelopmental disorders including epilepsy, dyskinesia, autism, Angelman’s syndrome, Fragile X syndrome, and brain and skeletal malformations." (PMID 35819138, 2022). "Neuronal hyperexcitability is coincident with establishment of an epileptic network, and about half of all individuals with KCNMA1 channelopathy, including those with N999S, D434G, and H444Q variants, report a history of seizures or epilepsy." (PMID 35819138, 2022). "On the other hand, stringent statistical standards have eliminated numerous KCNMA1 SNP variants from consideration such as disease-causing in epilepsy, hyperlipidemia, and alcohol dependence." (PMID 34224328, 2021). "Other genes and gene families showing monoallelic expression include the annexin gene family and the Thy1 gene, both linked to inflammation and cancer, as well as genes linked to alcohol dependence (Gabrg1) and epilepsy (Kcnma1)." (PMID 22384067, 2012). "KCNMA1 encodes one subunit of the large-conductance voltage- and Ca(2+)-activated K+ channel (BK channel), which is implicated in human epilepsy, blood pressure regulation, and the risk of myocardial infarction." (PMID 21708048, 2011). "KCNMA1-linked channelopathy, a rare disorder characterized by mutations in the KCNMA1 gene, presents as neurological and neuromuscular dysfunction – specifically epilepsy, paroxysmal dyskinesia, and neurodevelopmental deficiencies." (PMID 40785052, 2025). "It has been reported that gain-of function variants of KCNMA1 could cause GGE, the most common epilepsy in photosensitivity, so it was reasonable to believe that KCNMA1 might be responsible for photosensitivity." (PMID 36034301, 2022). "With respect to patient genetics, the variety of genes included across different epilepsy panels suggests that additional ion channel variants may have gone undetected in KCNMA1 patients, depending on the commercially available panel." (PMID 34224328, 2021). "Lastly, it remains unclear whether the neurodevelopmental problems are primary effects of KCNMA1 mutations, or secondarily resulting from epilepsy." (PMID 34224328, 2021). "This study expands the mutation spectrum of KCNMA1-epilepsy, explores the possible mechanism of epilepsy by transcriptome, reveals the relationship between KCNMA1-LOF and epilepsy, and provides a possible molecular template for individualized treatment of epilepsy." (PMID 35095492, 2021). "Mutations in KCNMA1 are associated with epilepsy and/or dyskinesia (PNKD3)." (PMID 31851553, 2020). "In conclusion, this report presents a unique case of a patient who manifested both phenotypes of the gain- and loss-of-function mutations of KCNMA1 (dyskinesia, epilepsy, and cerebellar atrophy) and had tegmental and spinal tract atrophy that has not been reported to date." (PMID 29545233, 2018). "Here, we report the case of a patient with a novel homozygous truncating mutation in KCNMA1 (p.Arg458Ter) presenting with both the loss- and gain-of-function phenotype with paroxysmal dyskinesia, epilepsy, intellectual delay, and corticospinal–cerebellar tract atrophy." (PMID 29545233, 2018). "It has been suggested that epilepsy can be caused by BK channel gain-of-function (GOF) and loss-of-function (LOF) mutations in the KCNMA1 gene." (PMID 38584598, 2024).
epilepsy (continued). "Epilepsy has been associated with mutations in the human gene orthologs of cac (CACNA1A/B/E), alpha-Spec (SPTAN1) and slo (KCNMA1)." (PMID 37759179, 2023). "The meta-regression analysis showed the strongest association of SCN2A with genes in neurodevelopmental disorders, and KCNMA1 as a common gene signature with a link to epilepsy, movement disorders and wide paroxysmal neurologic presentations." (PMID 37008993, 2023). "Correlation between patient genotype and phenotype has only been established for a single KCNMA1 variant so far, D434G, an autosomal dominant that co-segregates with PNKD and epilepsy in a multi-generation pedigree." (PMID 35819138, 2022). "Polymicrogyria was observed in patients with drug-resistant epilepsy and mutations in the Ca2+-activated K+ channel KCNMA1 (BK channel)." (PMID 35237124, 2022). "The initial report of pathogenic variants in KCNMA1 described the largest cohort of affected patients (15 family members) with p.Asp434Gly with a variable phenotype of PNKD and/or epilepsy." (PMID 34177764, 2021). "Looking into the DEG subnetwork, we found that some well-known ASD candidate genes, such as Kcnma1, Shank2, Cacna1a and Cacna1b, and epilepsy candidate genes, such as Scn3a, Grin2a, Gabrg2, and Grin2b, are hub genes in this subnetwork." (PMID 32033586, 2020). "Only one homozygous mutation, a stop-gain, was observed in single individual, in Potassium Calcium-Activated Channel Subfamily M Alpha 1 (KCNMA), a calcium-sensitive potassium channel gene which has been shown to have a role in general and early-onset epilepsy-related phenotypes." (PMID 36539902, 2022). "Recently, genetic screening identified heterozygous KCNMA1 variants in a subset of patients with debilitating paroxysmal non-kinesigenic dyskinesia, presenting with or without epilepsy (PNKD3)." (PMID 35819138, 2022). "Almost all patients with KCNMA1‐linked channelopathy exhibit PNKD, epilepsy, or both." (PMID 35141357, 2022). "However, KCNMA1 SNPs have been linked to multiple neurological disorders including ASD, epileptic encephalopathy, epilepsy, and Alzheimer’s Disease." (PMID 34224328, 2021). "In this study, the properties of BK channels encoded by KCNMA1 patient mutations associated with epilepsy and/or paroxysmal nonkinesigenic dyskinesia (PNKD) were investigated." (PMID 31851553, 2020). "Reportedly, mutations in KCNMA1 have been identified in clinical cases of epilepsy and paroxysmal nonkinesic dyskinesia." (PMID 29545233, 2018). "The core features of KCNMA1-related disorders (both GOF and LOF) are epilepsy, movement disorders, neurodevelopmental disorders and ID." (PMID 34177764, 2021). "Further analysis conducted on ATP1A2, SLC2A1, SLC2A2 KCNMA1 and KCNN3 showed they all are related to epilepsy or seizures." (PMID 27984588, 2016). "There is no associated epilepsy or neurodevelopmental disorder, in contrast to the PNKD phenotype associated with KCNMA1." (PMID 34177764, 2021).
breast carcinoma (31 papers, 2009 to 2026). "For example, in breast cancer, KCNMA1, KCNJ3, KCNN4, and KCNK9 are associated with estrogen receptor expression and lymph node and brain metastases; KCNMA1 is also overexpressed in hormone-sensitive prostate cancer cells." (PMID 41601884, 2026). "In large datasets of breast cancer patients, we identified a gene, KCNMA1 (encoding for a voltage- and calcium-dependent large-conductance potassium channel, called BK channel), overexpressed in triple-negative breast cancer patients." (PMID 32586284, 2020). "The large-conductance Ca2+-activated K+ channel KCa1.1 encoded by the KCNMA1 gene is overexpressed in breast cancer cells, and plays a crucial role in breast cancer proliferation, invasion, and metastasis." (PMID 29713287, 2018). "The BKCa channel encoding gene KCNMA1 is amplified in about 16% of late-stage prostate cancers and in about 1.9% of breast cancers." (PMID 25397596, 2014). "Amplification of KCNMA1 was found in 23 of 1200 breast cancers (1.9%) and was significantly associated with high tumour grade (p<0.001), high tumour cell proliferation (p<0.01) and poor tumour-specific survival (Log-Rank p = 0.031)." (PMID 22899999, 2012). "In this study we investigated the role of KCNMA1 gene that encodes for the pore-forming α-subunit of BKCa channels in breast cancer metastasis and invasion." (PMID 19640305, 2009). "Using microarrays, KCNMA1 gene expression was found to increase in several cancers including breast cancer." (PMID 32586284, 2020). "While KCNMA1 genes are overexpressed in all types of breast cancer, targeting it is particularly useful for TNBC due to lack of effective pharmacological therapy in TNBC patients." (PMID 32586284, 2020). "Previous studies have suggested a contradictory role of KCNMA1 in breast cancer proliferation, invasion, and metastasis." (PMID 32586284, 2020). "Using RNA-seq data in a large breast cancer dataset in TCGA, we found overexpression of KCNMA1 in all subtypes of breast cancer." (PMID 32586284, 2020). "Amplification of the KCNMA1 gene was observed in 16% of advanced prostate tumors and an up-regulation of its expression was observed in breast carcinoma, prostate cancer, glioblastoma, and cervical cancers." (PMID 30791468, 2019). "KCa1.1 is encoded by KCNMA1, and the amplification of KCNMA1 has been correlated with a high tumor stage and poor prognosis in breast cancer." (PMID 27973439, 2016). "For example, nuclear-mtDNA fusion in PD11372a occurred in the fifth intron of the KCNMA1 gene, a potassium channel frequently amplified in prostate and breast cancers." (PMID 25963125, 2015). "Recent studies demonstrate that KCNMA1 is amplified in several malignant diseases, including prostate cancer, breast cancer, ovarian and endometrium carcinoma, and contributes to high proliferation rate and malignancy." (PMID 25397596, 2014). "CRISP3 and KCNMA1 have been demonstrated to be correlated with metastasis potential in prostate cancer and breast cancer, respectively." (PMID 23451142, 2013). "Our findings revealed that enhanced expression of KCNMA1 correlates with and contributes to high proliferation rate and malignancy of breast cancer." (PMID 22899999, 2012). "KCNMA1-function in breast cancer cell lines was confirmed by whole-cell patch clamp recordings and proliferation assays, using siRNA-knockdown, BK channel activators such as 17ß-estradiol and the BK-channel blocker paxilline." (PMID 22899999, 2012). "Immunofluorescence revealed moderate or strong KCNMA1 protein expression in 8 out of 9 human breast cancers and in the breast cancer cell line MFM223." (PMID 22899999, 2012). "KCNMA1 was amplified in MFM223, a rapidly growing metastatic human breast cancer cell line, and associated with strongly up-regulated mRNA- and protein expression." (PMID 22899999, 2012). "The Global exon array and RT-PCR showed higher KCNMA1 expression in metastatic breast cancer in brain compared to metastatic breast cancers in other organs." (PMID 19640305, 2009).